RBPMS-AS1 (RBPMS antisense RNA 1)
Synonyms: TP53LC06
Gene: Long non-coding RNA gene on chromosome 8 (30,380,582 to 30,385,401, reverse strand). Ensembl gene ENSG00000254109.
Diseases named in the same sentence as RBPMS-AS1 in open-access papers:
RBPMS-AS1 is named in the same sentence as 1 disease in open-access papers, as found by Europe PMC text mining. Sharing a sentence is not in itself a finding about the gene and the disease. The quoted sentences say what the papers report.
cancer (1 paper, 2021). A tumor composed of atypical neoplastic, often pleomorphic cells that invade other tissues. "Several other lncRNAs, such as SERTAD4-antisense 1, LINC01124, AC011294.1 and RBPMS Antisense RNA 1, have also been associated with cancer initiation and prognosis." (PMID 34689838, 2021).